IL5 (interleukin 5)
Diseases named in the same sentence as IL5 in open-access papers (continued):
Sharing a sentence is not in itself a finding about the gene and the disease.
asthma (continued). "Of note, the equal IL-9 and IL-5 production in the CLA− T-cell coculture is of particular interest since anti-IL-5 therapy has proven to be successful in extracutaneous allergic diseases such as asthma, but not in AD, considered a CLA+-driven disease." (PMID 39201262, 2024). "In this case, dupilumab discontinuation was initially considered, but, in order to avoid resuming steroids and since previous anti-IL-5 mepolizumab monotherapy had failed to control asthma symptoms, it was chosen not to stop dupilumab and to add-on benralizumab." (PMID 38003909, 2023). "In T2-high asthma, the interaction of the airway epithelium with the external exposome activates the release of specific mediators—epithelial-derived alarmins—as thymic stromal lymphopoietin (TSLP), IL-25, and IL-33, leading to the production of IL-4, IL-5, and IL-13." (PMID 37761964, 2023). "Similarly, against IL-5, reslizumab was able to reduce asthma exacerbations and OCS intake in treated patients; unlike other drugs, it was administered intravenously, which is a method that is yet to be approved in several countries." (PMID 37765327, 2023). "The magnitude of change in SCFAs required to affect biomarkers is unknown, as we did not assess asthma-specific markers of inflammation in serum such as eosinophils, leukotrienes, or IL-5." (PMID 37384109, 2023). "In a chemical-induced asthma model, NAC reduced the toluene diisocyanate-induced airway hyperresponsiveness and metaplasia of goblet cells, decreased the lung infiltration by neutrophils and eosinophils, lowered the production of IL-4 and IL-5, and attenuated the redox imbalance." (PMID 37760016, 2023). "In contrast, the efficacy of anti–IL-5 biologics on CRSwNP outcomes (such as the polyp size) does not seem to differ whether patients had comorbid asthma or not." (PMID 37035303, 2023). "Eosinophilia can identify asthmatic patients who may benefit more significantly from ICS therapy, and monoclonal antibodies targeting IgE or the type 2 cytokines (IL‐4, IL‐5 and IL‐13) or alarmins (IL‐33, TSLP) benefit patients with the ‘Type‐2‐high’ phenotype of asthma." (PMID 37963721, 2023). "Specifically, in an OVA-induced murine asthma model, intranasal treatment with a polyclonal rabbit anti-ALCAM antibody at the time of OVA challenge reduced allergic symptoms, such as the leukocyte count and Th2 cytokine (i.e., IL-4, IL-5, and IL-13) levels in BAL fluid." (PMID 37514028, 2023). "Our experimental results indicated that MS ameliorated asthma-induced AHR and decreased cellular infiltration in the lung epithelium, decreased EOS cell counts in BALF and the lungs, lowered proinflammatory CK (IgE, IL-4, and IL-5), and augmented anti-inflammatory CK (IL-10) expression." (PMID 35812246, 2022). "In studies in real life, concerning the efficacy of anti-IL-5 drugs, regardless of the number of eosinophils, provided that above 300 cells/μl, B-EOS correlated with risk of asthma exacerbations, the decline in respiratory function, mortality, and systemic corticosteroid dependence." (PMID 36300189, 2022). "Consequently, the pre-pruned decision tree model; based on the levels of IL-5 in NasSec (≤ 15.04 pg/mL), blood eosinophil count (≤ 0.475*109/L) and absence of comorbid asthma; was chosen to define Th2lowCRSwNP from Th2highCRSwNP for routine clinical use." (PMID 36618395, 2022). "Unlike antibodies that target IL-5, benralizumab reduces eosinophils more efficiently via antibody-dependent cell-mediated cytotoxicity, resulting in the improvement of lung function or asthma control." (PMID 36403040, 2022). "Notably, no direct head-to-head comparisons between anti-IL-5 antibodies in asthma have been made, although one head-to-head study comparing benralizumab and mepolizumab in Eosinophilic Granulomatosis With Polyangiitis is ongoing (MANDARA)." (PMID 36561741, 2022).
asthma (continued). "The reduction in the release of damaging eosinophil content by augmenting airway autophagy may be of importance in eosinophilic diseases, including asthma, particularly in the absence of IL5 signaling." (PMID 35681515, 2022). "Studies have shown that patients with peripheral blood eosinophilia (≥150/μL) benefit more from anti-IL-5 therapy, and it is therefore recommended for severe asthma with marked eosinophilia, regardless of whether it is allergic or not." (PMID 36560478, 2022). "Endotype, sex, age, asthma history, LM score, GOS score, sinus dominance, olfactory CT score, tissue eosinophilia, HNE subepithelial count, HNE perivascular count, serum eosinophil, IL5, IL6, INFγ, TNFɑ, and IL10 saw significant differences between the two groups." (PMID 36428479, 2022). "In addition to synergistically acting together with Th2 cells in allergic asthma, ILC2 are the most relevant cellular sources of IL-5 in non-allergic eosinophilic asthma, whose clinical manifestations often start in adulthood (late-onset asthma)." (PMID 35625801, 2022). "However, it should be mentioned that under certain conditions, breast milk contains allergens and cytokines (IL-4, IL-5, IL-13, TGF-β, etc.)that might contribute to the development of asthma and airway wall remodeling." (PMID 34834581, 2021). "Another study following patients receiving anti-IL-5 treatment for two years, showed that adult onset, absence of nasal polyposis, FEV1 ≥ 80% predicted, asthma duration < 10 years, and BMI < 25 were baseline characteristics that predicted a super-response to anti-IL-5 treatment." (PMID 35008504, 2021). "Despite recent studies demonstrating that anti-IL-5 treatment reduced airway eosinophil numbers without necessarily modifying the functionality of the remaining eosinophil cells, anti-IL-5 was used in a clinical setting to reduce asthma exacerbation." (PMID 34445627, 2021). "Furthermore, in an OVA-induced asthma model, ArtC treatment reduced pulmonary inflammation, eosinophil influx to the airways, mucus and IL-5 secretion along with increased frequency of M-MDSC, but not Treg cells, in the lungs." (PMID 34834178, 2021). "The numbers of inflammatory cells and the levels of T2 cytokines (IL-4, IL-5, IL-13, and IL-33) in BALF were increased in the LTE4-alone, OEA-alone, and LTE4-pretreated groups, and these factors play important roles in airway inflammation and asthma remodeling." (PMID 34079051, 2021). "The current add-on treatment options for severe asthma are long-acting muscarinic antagonist (LAMA), leukotriene modifier, low dose azithromycin, and low dose oral corticosteroids (OCS), and biological drugs such as anti-IgE, anti-IL-5/IL-5R, or anti-IL-4R for type 2 severe asthma." (PMID 35387016, 2021). "However, the amount of OVA-specific IgE, IL-5, and IL-13 in BALF obtained from macrophage-Arf6 cKO mice decreased compared with that obtained from WT mice, suggesting that macrophages exacerbate asthma-like allergic inflammation through Arf6." (PMID 34423792, 2021). "There are numerous other pathways, aside from the IL-5-eosinophil pathway which may contribute to asthma pathogenesis but may not be adequately attenuated by IL-5-targeted biologics." (PMID 35126131, 2021). "Furthermore, this strain was found to protect better against allergen-induced eosinophilia and IL-5 production than non-recombinant BCG in a murine model of experimental ovalbumin-induced asthma." (PMID 33803752, 2021). "It is conceivable that IL-5 blockade could treat the asthma and eosinophil-driven aspect of the disease without impacting on vasculitis, thereby allowing EGPA to develop despite treated asthma." (PMID 34124538, 2021). "In addition to Th17 cells and Treg cells, many immunoregulatory cells, such as Th2 cells, Th1 cells, innate lymphoid cells, dendritic cells, natural killer T cells, and TH9 cells, and many endogenous cytokines related to asthma, such as IL4, IL-5, IL13, IL22, and IL25, are also involved." (PMID 32620122, 2020).
asthma (continued). "At present, our data suggest that high β2-agonist reversibility might not be the best predictor of response to anti-IL-5 treatment while low β2-reversibility (in the presence of a marked eosinophilia) might be indicative of eosinophil-dependent asthma." (PMID 32328116, 2020). "However, IL-5 is recognized as an effective biomarker for other diseases in which eosinophilia is detected; therefore, its role as a biomarker for asthma severity is not yet defined." (PMID 31438916, 2019). "However, BAL IL-5 levels were significantly elevated for both obese (n = 10) and non-obese asthma (n = 12) patients." (PMID 31836714, 2019). "However, there is a lack of evidence regarding the influence of asthma medication, including corticosteroids, on IL-5 and IL-13 production in a co-culture system." (PMID 31861989, 2019). "However, in clinical practice, the frequency and severity of asthma symptoms may not always be associated with eosinophil count, particularly in patients with blood eosinophilia close to the cut-off point identified as the predicting marker for prescribing an anti-IL-5 strategy." (PMID 29879991, 2018). "It is generally believed that in types of asthma with high eosinophilia (frequently non-allergic types), an anti-IL-5 strategy could be considered as the first choice of treatment." (PMID 29879991, 2018). "For Global Initiative for Asthma (GINA) Step 5 patients, a targeted therapy approach is recommended; omalizumab, a humanised mAb that selectively targets IgE, and mepolizumab and reslizumab, two additional humanised mAbs targeting IL-5, are available treatment options." (PMID 29879991, 2018). "Furthermore, its clinical effect is independent of the IL-5 circulating levels, which usually tends to increase during asthma exacerbations." (PMID 29992143, 2018). "Cytokines including interleukin 4 (IL-4), interleukin 5 (IL-5), IL-6, IL-8, interleukin 10 (IL-10), monocyte chemoattractant protein (MCP)-1/CCL2, and thymus and activation-regulated chemokine (TARC)/CCL17 trigger secondary inflammatory events, aggravating asthma pathogenesis." (PMID 29755573, 2018). "With an excellent safety profile and the requirement for long-term if not life-long treatment, IL-5 might be an ideal target for the development of an active vaccine against asthma and potentially COPD." (PMID 30405579, 2018). "This study was performed before anti-IL5 monoclonal antibodies were available for clinical use but the results demonstrate that most patients would not require them for improving asthma control but they would be useful to avoid the adverse effects of corticosteroids." (PMID 28396690, 2017). "Thus the addition of CXCL-1, IFN-γ, IL-5, IL-17A, EGF, eotaxin, IL-lβ, IL-4, IL-12p40, IL-13, and MDC serum concentrations to blood eosinophils and neutrophils adds significant value to the definition of the Difficult-to-Control asthma endotype." (PMID 28686637, 2017). "The treatment with recombinant mouse B7-H3 significantly increased the IL-4 (29.34 ± 4.67 pg/mL), IL-5 (17.64 ± 0.84 pg/mL), IL-13 (421.31 ± 53.60 pg/ml) and IFN-gamma (266.01 ± 32.72 pg/ml) concentration in BALF as compared with mice in the wild-type group with asthma (P < 0.05)." (PMID 28094276, 2017). "The experimental model for the induction of asthma has increased cellularity in the BAL represented by eosinophils, lymphocytes and neutrophils, as well as an increase in cytokines with a Th2 profile (IL-4 and IL-5), together with the production of mucus in the airways." (PMID 29145431, 2017). "Moreover, we found a much higher secretion of IL-5, IL-13 and IL-25 in the asthma group (P< 0.05), while no significant changes in the anti-IL-25 group were observed (P> 0.05)." (PMID 27617447, 2016). "Previously, Jung and colleagues found that KWG could inhibit the infiltration of inflammatory cells in ovalbumin (OVA)-induced allergic mouse model of asthma, and decrease OVA-specific IgE and IL-4, IL-5, and IL-13 in the sera and bronchoalveolar lavage fluids." (PMID 27879681, 2016).
asthma (continued). "Depletion of T cells in sensitized mice inhibits asthma pathology including eosinophil recruitment to the lungs, and the absence of eosinophils decreases IL-4, IL-5 and IL-13 production, and also impairs T cell recruitment/accumulation of effector T cells to the lungs." (PMID 27203689, 2016). "However, blocking Th2 cytokines such as IL-4, IL-5, and IL-13 despite not been completely explored has shown some promising results in selected patients with asthma." (PMID 26334389, 2016). "Thus, it has been questioned whether blocking IL-25 against its receptor IL-17BR could inhibit the expression of IL-13 and IL-5 via nuocytes, and further protect against inflammation in ovalbumin (OVA) induced mouse-model of asthma." (PMID 27617447, 2016). "Not surprisingly, the underlying airway pathology of atopic versus nonatopic asthma is different, showing high numbers of eosinophils, T lymphocytes and Th2 cytokines (interleukin (IL)-4 and IL-5) in atopic asthma versus high numbers of neutrophils and non-Th2 cytokines (IL-8) in nonatopic asthma." (PMID 27552197, 2016). "So far, asthma therapy uses drugs which alleviate the symptoms but do not inhibit the mechanism responsible for the expression of inflammatory mediators such as the cytokines interleukin-4 (IL-4), interleukin-13 (IL-13) and interleukin-5 (IL-5)." (PMID 26117852, 2015). "In sputum neither IL-5 nor IL-13 levels were increased in patients with mild or moderate asthma." (PMID 25746968, 2015). "Asthma had no significant impact on the scores in the IL-5 and SE-IgE positive NPs." (PMID 26275068, 2015). "The pathogenesis of asthma is directed by allergen-specific Th2 cells generated in the secondary lymphoid organs such as the BLN, and the migration of Th2 cells into lung plays an important role in mobilization of eosinophils via the secretion of IL-4 and IL-5." (PMID 26488300, 2015). "A comparison of salivary marker concentrations between adults with and without asthma shows that IL-5, IL-6, MCP-1, and VEGF concentrations were present in statistically significantly higher concentrations in saliva collected from asthmatics compared to controls, and the other markers were not." (PMID 24409298, 2014). "While the IL5 and PON2 genes showed an association only with allergic asthma, none of the studied genetic polymorphisms was found to be associated exclusively with the risk of nonallergic asthma." (PMID 24895604, 2014). "Firstly, noneosinophilic or neutrophilic airway inflammation might contribute to persistent asthma symptoms in patients treated with inhaled corticosteroids, and such patients would be unlikely to respond to anti–IL-5 treatment." (PMID 23544105, 2013). "In vivo, the KIM-127 signal of blood eosinophils was decreased in subjects with non-severe asthma after administration of anti-IL-5 mepolizumab, indicating that the intermediate conformation of β2 integrins on blood eosinophils is the result of exposure to IL-5 in the bone marrow and/or circulation." (PMID 23554594, 2013). "Moreover atopic and non-atopic asthma phenotypes were significantly influenced by IL-5 levels (OR for atopic asthma 1.96 (1.09–3.52, p = 0.025)." (PMID 21179211, 2010). "Other biologic agents targeting IL-5, and IL-4/IL-13 did not demonstrate any serious or severe treatment-related adverse events in asthma patients, There has been some conflicting information on the safety of TNF-alpha blocking agents in the treatment of asthma." (PMID 20016776, 2009). "In a mouse asthma model, BALB/c mice treated with imiquimod cream containing siNPRA chitosan nanoparticles showed significantly reduced airway hyperresponsiveness, eosinophilia, lung histopathology and pro-inflammatory cytokines IL-4 and IL-5 in lung homogenates compared to controls." (PMID 18279512, 2008).
asthma (continued). "For example, clinical resolution of human asthma could not be demonstrated by targeting eosinophils with anti-IL-5 therapy, despite the many studies in animal models that have shown the success of IL-5 neutralization in blocking experimental asthma." (PMID 17897475, 2007). "However, while IgE levels are not typically used for guiding anti-IL5/5Rα therapy, it is noteworthy that benralizumab was able to reduce total IgE levels correlated with a reduction in basophils (but not eosinophiles) and with an improvement in asthma control." (PMID 39063652, 2024). "In this regard, it has been shown that tissue eosinophils that are found in large numbers in COPD exacerbations and in smaller numbers in stable COPD are not accompanied by an increase in IL-5, suggesting that they may have different functions and recruiting mechanisms than eosinophils in asthma." (PMID 39063652, 2024). "Hence, blocking the IL-5 pathway may be a good treatment option for patients with asthma and elevated blood eosinophils when ICS does not control the disease." (PMID 40980110, 2023). "Our finding of interleukin production as a top PBMC asthma module is not surprising, given the broad representation of this module and the pervasive roles that interleukins play in orchestrating inflammatory processes in asthma, including IL-4, IL-5, and IL-13 in type 2 inflammation." (PMID 37730635, 2023). "However, some studies have reported higher levels of airway IL-5 and eosinophils in obese patients in general, and the Severe Asthma Research Program (SARP) has also identified a group of predominantly females with severe late-onset asthma, obesity, and increased sputum eosinophils." (PMID 37108417, 2023). "Blood-circulating IL-5 and especially GM-CSF levels are enhanced in asthma; therefore, it might be related to significantly lower GM-CSFR mRNR levels in blood eosinophil subtype-like cells in asthma and less activation of eosinophil by GM-CSF in our in vitro model." (PMID 36497064, 2022). "Interestingly, the expression of BIRC3 in GSE76262 was significantly positively correlated with inflammatory cytokines IL-4, IL-5, IL-13, and IL-25 expression (p < 0.05), which implied that BIRC3 may play an important role in the pathogenesis of inflammation in asthma." (PMID 35287655, 2022). "Moreover, in a chronic model murine of asthma (MMA), muscarinic antagonists were found to decrease smooth muscle mass in addition to ICS, low cell counts (macrophages, eosinophils, and lymphocytes), and decreased IL-5 levels in BALF than other Th2-profile cytokines." (PMID 34055794, 2021). "Another limitation of using gene expression profiling of selected cytokines (IL4, IL5, and IL13) in induced sputum for asthma stratification in comparison to unsupervised approaches employing several biomarkers is that prevalence of T2-high asthma might be underestimated." (PMID 33513844, 2021). "As basophils and mast cells can produce β-HEX, IL-4 and IL-5 after allergen stimulation, and secreted enzymes such as tryptase can induce the release of β-HEX from eosinophils in the blood, these molecules may engage in both the induction and exacerbation of asthma through positive feedback loops." (PMID 33036262, 2020). "β-HEX’s positive association with IL-5/IL-13 (known promoters of the Th2 response), negative association with IGFBP-1 and IgG2, elevated stability in plasma, and low cost of measurement advocate for the use of β-HEX as a routine biomarker for severe asthma in pediatrics." (PMID 33036262, 2020). "However, in the 1980s, the notion that asthma was nearly always atopic came into prominence, which lead to the use of asthma as an exemplar TH2-mediated atopic disease characterized by TH2 cytokines like IL-4, IL-5 and IL-13, eosinophilia and increased IgE production." (PMID 31120919, 2019).